SIRT1 (sirtuin 1)
Diseases named in the same sentence as SIRT1 in open-access papers (continued):
Sharing a sentence is not in itself a finding about the gene and the disease.
vitamin D deficiency (12 papers, 2017 to 2025). A nutritional condition produced by a deficiency of VITAMIN D in the diet, insufficient production of vitamin D in the skin, inadequate absorption of vitamin D from the diet, or abnormal conversion of vitamin D to its bioactive metabolites. "Future studies should incorporate these functional assessments to provide a more comprehensive understanding of how Sirt1 overexpression affects not only muscle mass but also muscle strength and performance in the context of vitamin D deficiency." (PMID 40168539, 2025). "Further well-designed RCT with relatively larger sample size and longer follow-up period are needed to understand the effect of vitamin D supplementation on lipid profile and SIRT-1 in obese patients with vitamin D deficiency." (PMID 31777705, 2019). "Furthermore, the VDR, when bound to its promoter, increases SIRT1 gene expression in kidney and liver cells, and vitamin D deficiency can lower both the SIRT1 level and activity." (PMID 40284214, 2025). "Our results point to SIRT1 as a critical effector of 1,25(OH)2D3 and rise the hope that acting on SIRT1 may circumvent 1,25(OH)2D3 unresponsiveness derived from vitamin D deficiency or VDR loss as it is common in advanced CRC." (PMID 39494323, 2024). "Vitamin D deficiency, through decreased SIRT1 level, led to increased fat deposition in adipocytes and macrophage infiltration parallel with increased proinflammatory cytokine IL-6 and TNFα as well as decreased PGC1α, an important molecular partner of the SIRT1/PGC1α antioxidant pathway." (PMID 37047134, 2023). "Finally, vitamin D and SIRT1 function have been recognised as critical for multiple diseases with inflammatory components 71,72, therefore, our conclusions may extend beyond cancer and suggest a potential for SIRT1 activators to alleviate the effects of vitamin D deficiency in multiple systems." (PMID 39494323, 2024). "Vitamin D insufficiency (HF+LVD) significantly reduced both SIRT1 gene expression and activity compared to the HF group." (PMID 28353634, 2017). "In addition, we found that diet-induced vitamin D insufficiency significantly decreased both SIRT1 expression and activity, consistent with our previous in vitro study." (PMID 28353634, 2017). "Eugene Chang found that vitamin D deficiency was significantly associated with adipose tissue increase, macrophage infiltration and inflammation in obese rats, and proved, for the first time, that vitamin D deficiency could reduce the activities of AMPK and Sirt1 in the adipose tissue of obese rats." (PMID 35956309, 2022). "In this scenario, the decrease in VDR due to predisposing genetic or environmental factors, as well as vitamin D deficiency, could have a negative effect on the transcription of SIRT1 and could influence all the pathways underlying DN regulated by this protein." (PMID 39976627, 2025).
abdominal aortic aneurysm (11 papers, 2019 to 2025). Enlargement and ballooning of the vessel that supplies arterial blood to the abdomen, pelvis and legs. "Accordingly, calorie restriction was found to be associated with SIRT1 activation in VSMCs and decreased prevalence of abdominal aortic aneurysm." (PMID 32977446, 2020). "SIRT1 was up‐regulated in VSMCs in response to CR and removing SIRT1 specifically in smooth muscle cells eliminated CR's preventive effect on abdominal aortic aneurysm formation." (PMID 41180381, 2025). "m6A modification promotes the maturation of miR-34a, which in turn inhibits SIRT1 expression and promotes the formation of abdominal aortic aneurysms." (PMID 37178254, 2023). "Accordingly, knockdown of METTL3 protects from development of abdominal aortic aneurysm, and this therapeutic effect is inhibitable by either miR-34a silencing or SIRT1 overexpression." (PMID 35991314, 2022). "Important agreeing studies revealed down-regulated SIRT1 expression in VSMCs of patients suffering from abdominal aortic aneurysm, while SIRT1 activation was accompanied by the inhibition of cell senescence and diminished vascular inflammation." (PMID 32977446, 2020). "Licochalcone A also attenuates angiotensin II-induced abdominal aortic aneurysm in mice by modulating miR-181b/SIRT1/HO-1 signaling." (PMID 31226782, 2019). "In VSMCs, age-related SIRT1 reduction is linked with vascular senescence and inflammation and formation of abdominal aortic aneurysms, while SIRT1 overexpression provides a therapeutic target by diminishing NF-κB binding on the promoter of MCP-1 and blocking vascular inflammation." (PMID 41011644, 2025). "Furthermore, METTL3 has been shown to promote Ang II- and CaCl2-induced abdominal aortic aneurysm by accelerating primary microRNA-34a maturation and inhibiting SIRT1 expression 33, and METTL3 also exacerbates oscillatory stress-induced atherogenesis." (PMID 35844806, 2022). "Similarly, mouse macrophage specific knockout of SIRT1 exacerbated abdominal aortic aneurysm formation." (PMID 34099590, 2021). "The development and progression of abdominal aortic aneurysm has been suggested to be induced through METTL3-mediated maturation of miR-34a and decreased Sirtuin 1 (Sirt1) mRNA expression." (PMID 35991314, 2022).
acute pancreatitis (11 papers, 2020 to 2025). An acute inflammatory process that leads to necrosis of the pancreatic parenchyma. "In conclusion, we found that VB 12 protected acute pancreatitis associated with oxidative stress via CBS/SIRT1 pathway." (PMID 34925701, 2021). "The SIRT1 activator resveratrol improved mitochondrial biogenesis by activating SIRT1/PGC1α signaling in severe acute pancreatitis, eliminated autophagosomes in cardiomyocytes, and slowed down the pathogenesis of neurodegenerative diseases as well as aging." (PMID 40989573, 2025). "In experimental acute pancreatitis models, both in vivo and in vitro experiments demonstrated that metformin restored impaired autophagy by upregulating SIRT1 expression mainly through AMPK activation, thereby reducing the release of inflammatory factors." (PMID 37928155, 2023). "In addition, Nim has been suggested to exert strong anti‐inflammatory and antiapoptotic effects on cerulein‐induced acute pancreatitis via SIRT1 activation." (PMID 40375435, 2025). "Interestingly, recent studies have shown that Nim exerts protective effects via a SIRT1‐dependent mechanism in disc degeneration, acute pancreatitis and chronic pancreatitis." (PMID 40375435, 2025). "Resveratrol (RSV), one of the SIRT1 agonists, has the ability of alleviating severe acute pancreatitis (SAP); however, the concrete protective mechanism remains unknown." (PMID 33628394, 2021). "Our study provides basic evidence that targeting CBS/SIRT1 pathway might be a therapeutic strategy for acute pancreatitis." (PMID 34925701, 2021). "Finally, we further verified the important role of SIRT1 signal axis in acute pancreatitis." (PMID 34925701, 2021). "Overall, metformin can exert protective effects in atherosclerotic thrombotic disease, intestinal inflammation, cardiovascular disease, asthma, acute pancreatitis, and diabetic nephropathy upon acting on the AMPK/NF-κB, AMPK/PTEN, AMPK/NLRP3, and AMPK/SIRT1 pathways." (PMID 37928155, 2023). "In the current study, the aims of this study were to determine (I) whether VB 12 attenuates the pathological damage of acute pancreatitis by CBS and (II) whether VB 12 inhibited oxidative stress and remedy mitochondrial dysfunction in acinar cells via CBS/SIRT1 signaling." (PMID 34925701, 2021).
aneurysm (11 papers, 2018 to 2026). Bulging or ballooning in an area of an artery secondary to arterial wall weakening. "The median SIRT1 value was found to be the highest in the aneurysm group at 214 (IQR79 - 270); intermediate in the dissection group at 172 (IQR 148 - 224); and thelowest in the control group at 104 (IQR 78 - 123)." (PMID 41259217, 2026). "In our study, when comparing SIRT1 levels in the aortic tissuesof the three groups (aneurysm, dissection, and control), the highest level wasobserved in the aneurysm group, followed by the dissection group, andthe lowest level was in the control group (P = 0.014)." (PMID 41259217, 2026). "Multiple studies have reported that SIRT1 expression is reduced in aortic dissection or aneurysm, and the upregulation of SIRT1 in endothelial cells or smooth muscle cells can block the occurrence of diseases by reducing cellular oxidative stress and inflammatory responses." (PMID 39010253, 2024). "Taken together, these well-established anti-oxidant effects of SirT1 are consistent with the findings that VSM-specific SirT1 deletions in mice, and decreased expression of SirT1 in human aorta, are associated with aortic dissection or aneurysms." (PMID 32982786, 2020). "This indicates not only the complex contribution of sirtuins to aneurysm pathobiology as a whole but may also complicate pharmacological treatment, particularly with regard to the use of pharmacological SIRT1 agonists versus use of SIRT1 antagonists for AA treatment." (PMID 39768700, 2024). "In the context of aneurysms, similar to how METTL14 promotes DGCR8-mediated processing of pri-miR-19a in atherosclerosis, METTL3-dependent m6A methylation promotes primary miR-34a maturation through DGCR8, leading to decreased SIRT1 expression and an aggravated aneurysm formation." (PMID 40005339, 2025).
endotoxemia (11 papers, 2013 to 2025). "In line with this notion, the deacetylation-mediated interaction of HMGB1 and SIRT1 in mice was sufficiently potent to robustly protect against endotoxemia in response to LPS challenge by inhibiting the secretion of HMGB1 and cytokines such as TNF-α and IL-6." (PMID 26522327, 2015). "Here, we report that HMGB1 release is modulated by SIRT1 in macrophages and an animal model of endotoxemia." (PMID 26522327, 2015). "Infection of Ad-Flag-HMGB1K282930R and Ad-Myc-SIRT1 conferred significant protection against lethality and improved survival during endotoxemia (survival rate, 85.7%) compared to infection of Ad-Flag-HMGB1K282930R alone (survival rate, 15.3%)." (PMID 26522327, 2015). "BALB/c mice infected with Ad-Flag-HMGB1, Ad-Flag-HMGB1K282930R, and/or Ad-Myc-SIRT1 via the tail vein were challenged with LPS to induce lethal endotoxemia." (PMID 26522327, 2015). "In the present study, we used a mouse model of endotoxemia to investigate the role of Sirt1 in inflammatory kidney injury." (PMID 24896770, 2014). "In summary, Sirt1 plays a protective role against inflammatory kidney injury in endotoxemia." (PMID 24896770, 2014). "SIRT1 overexpression using SIRT1 expressing adenovirus significantly improved mouse survival rates (66%) after LPS-induced endotoxemia, compared with control LacZ expressing adenovirus-injected mice (26%) as determined on day 6 (middle) (log-rank test, P < 0.05)." (PMID 24573134, 2014). "SIRT1 inhibited LPS- or TNF-α-induced HMGB1 release from macrophages by directly interacting with HMGB1 in an acetylation-dependent manner; therefore, we next analyzed whether SIRT1 affected the circulating HMGB1 level during endotoxemia, a standard model of systemic inflammation." (PMID 26522327, 2015). "SIRT1 may affect LPS-mediated signaling pathways and endotoxemia." (PMID 24573134, 2014). "In order to further illustrate the mechanisms of how AC-Rsv exhibited the protecting effects against the endotoxemia induced by LPS, the expression of MAPK/SIRT1 pathway was evaluated by western blot." (PMID 26648661, 2015). "Furthermore, PPARγ-mediated upregulation of SIRT1 expression participates in the inhibitory action of PPARγ through deacetylation-mediated interaction of SIRT1 and HMGB1, leading to improvement of the survival of endotoxemia model mice." (PMID 28403838, 2017).
gestational diabetes (11 papers, 2018 to 2026). Carbohydrate intolerance first diagnosed during pregnancy. "In addition, downregulated SIRT1 has been reported to be associated with gestational diabetes and to play a possible role in reducing hypervascularization early in pregnancy and protecting against subsequent pregnancy complications caused by impaired placental growth." (PMID 37695462, 2024). "Strategies that target activation of SIRT1 could have a role mitigating fatty acid dyslipidemia in pregnancies complicated by gestational diabetes." (PMID 32365792, 2020). "Also, gestational diabetes-mediated inhibition of Sirt1 is epigenetically regulated through DNA hypermethylation in the fetal heart and that inhibitors of DNA methylation enhance Sirt1 expression." (PMID 35387565, 2022). "In conclusion, the present study demonstrates that high glucose and insulin levels of the GDM environment decrease DHA transport through the trophoblasts via decreased SIRT1-mediated signaling, providing a molecular mechanism linking gestational diabetes and decreased transplacental DHA transport." (PMID 32365792, 2020). "In a previous study, we observed decreased SIRT1 and SIRT4 transcript levels in fetal endothelial cells and HUVECs from pregnancies complicated by gestational diabetes, where a hypoxic component can also be postulated." (PMID 32796661, 2020). "Of course, further studies are required to clarify whether leukocyte SIRT1 and G6PD up-regulation might mediate antioxidative effects during gestational diabetes." (PMID 30513672, 2018). "Importantly, gestational diabetes mellitus (GDM) exposure can induce OS of cardiac myocyte in offspring and excessive ROS selective activation and increase DNA methyl transferase expression, thereafter leading to DNA hypermethylation, downregulating Sirt1 protein expression and Akt phosphorylation." (PMID 35103095, 2022).
idiopathic pulmonary fibrosis (11 papers, 2020 to 2025). Idiopathic pulmonary fibrosis (IPF) is a nonneoplastic pulmonary disease that is characterized by the formation of scar tissue within the lungs in the absence of any known cause. "Sirt1 plays a significant role in both bleomycin-induced fibrosis and idiopathic pulmonary fibrosis (IPF)." (PMID 35874275, 2022).
infarction (11 papers, 2017 to 2023). A localised pathological necrosis of tissue resulting from obstruction of the blood supply usually by a thrombus, an embolus, or vascular torsion. "We have reported that the age‐related deficiency of SIRT1 exacerbated cardiac systolic dysfunction with enlarged infarction size and metabolic disorder upon I/R stress." (PMID 34216536, 2021). "The deletion of cardiomyocyte SIRT1 (icSIRT1−/−) versus SIRT1f/f mice also showed a larger infarction size after myocardial I/R stress." (PMID 37537789, 2023). "The results of this study demonstrated that AS-IV can improve neurological dysfunction, decrease infarction area, upregulate the expression of SIRT1, and decline the levels of ac-MAPT and p-MAPT." (PMID 33841157, 2021). "In this context, SIRT1 activator arctigenin promotes a reduction in infarction volume and thus alleviates pro-inflammatory responses and oxidative stress." (PMID 32727328, 2021). "On the contrary, SIRT1-specific inhibitor EX527 hindered the improvements of neurological function, infarction area, and the changes of modified MAPT levels caused by AS-IV." (PMID 33841157, 2021). "Infarction volume has also been shown previously to be regulated through SIRT1 expression." (PMID 32727328, 2021). "Baseline serum sirtuin 1, 3 and 6 levels were similar in thepatients with and without pre-infarction angina." (PMID 31291416, 2019). "In addition, in our study, the inability of EX-527, a selective SIRT1 inhibitor, to block PTS-induced apoptosis in the penumbra and reduce infarction volume revealed that SIRT1 is not involved in the mouse cerebral cortex response to photothrombotic stroke." (PMID 35574497, 2022).
renal cell carcinoma (11 papers, 2018 to 2024). "The activation of SIRT1 can inhibit the malignant behavior of renal cell carcinoma cells by restoring the activity of AMPK and inducing cell apoptosis, thereby weakening the invasiveness and migration ability of tumor cells." (PMID 39845948, 2024). "In the present study, we discovered the suppressive role of MOF in tumor progression through regulating the expression of SIRT1, and provides a potential therapeutic target for renal cell carcinoma." (PMID 35252011, 2022). "A recent study found that the ethanol extract of Patrinia scabiosaefolia induces the death of human renal cell carcinoma 786-O cells via SIRT1 and mTOR signaling-mediated metabolic disruptions." (PMID 34194607, 2021). "Furthermore, in both normal kidney and Renal Cell Carcinoma (RCC) cells, lactate has been found to increase global H3 and H3K9ac by inhibiting SIRT1, a class of histone deacetylase." (PMID 38992327, 2024). "Another study showed that SIRT1 inhibited renal cell carcinoma (RCC) cell proliferation by inhibiting the expression of the FGB gene, and overexpression of FGB rescued inhibition of SIRT1 overexpression on the proliferation of RCC cells." (PMID 38213743, 2024). "SIRT1 deacetylates STAT3, which promotes the degradation of STAT3 and leads to the suppression of tumorigenesis in renal cell carcinoma (RCC)." (PMID 34769241, 2021).
atrial fibrillation (10 papers, 2014 to 2025). A disorder characterized by an electrocardiographic finding of a supraventricular arrhythmia characterized by the replacement of consistent P waves by rapid oscillations or fibrillatory waves that vary in size, shape and timing and are accompanied by an irregular ventricular response. "A study showed that fenofibrate, clinically used to reduce lipid levels, prevented rabbits with atrial fibrillation from atrial metabolic remodeling through the SIRT1-SREBP1 pathway." (PMID 31299012, 2019). "In the first study, conducted by our group, SIRT1 protein was increased in cardiac tissue of patients suffering from postoperative atrial fibrillation, likely to compensate the deleterious effects of tissue hypoxia during/after surgery." (PMID 31143479, 2019). "In addition, the close relationship between SIRT1 expression in atrial tissue and atrial fibrosis in patients with atrial fibrillation has also been reported." (PMID 33906673, 2021). "Moreover, the decreased steady state of miR-199a, with subsequent activation of the SIRT1 protein, might predict postoperative atrial fibrillation." (PMID 34943265, 2021).
chronic lymphocytic leukemia (10 papers, 2011 to 2025). "In addition, a recent work showed that treatment of chronic lymphocytic leukemia cells with nicotinamide blocks the deacetylating activity of endogenous SIRT1 leading to an inhibition of proliferation and to the activation of apoptosis." (PMID 23990942, 2013). "It has been reported that SIRT1 inhibitor restrained cell growth with IC50 ranging from 50–100 μM in MEC-2 and JVM-3 B-cell chronic lymphocytic leukaemia cell lines." (PMID 39935420, 2025). "Another study showed that SIRT1 and SIRT2 contribute to the pathogenicity of chronic lymphocytic leukemia (CLL)." (PMID 35406621, 2022). "Overexpression of SIRT1 is also found in chronic lymphocytic leukemia (CLL)." (PMID 30377410, 2018). "SIRT1 was found to be overexpressed in AML and in B-cell chronic lymphocytic leukemia (B-CLL), and downregulated during neutrophil differentiation of acute promyelocytic leukemia cells." (PMID 21818379, 2011).